BDNF (brain derived neurotrophic factor)
Diseases named in the same sentence as BDNF in open-access papers (continued):
Sharing a sentence is not in itself a finding about the gene and the disease.
meningioma (2 papers, 2019 to 2024). A generally slow growing tumor attached to the dura mater. "Expression of BDNF mRNA and associated signaling molecules were determined by evaluating cochlear cDNA libraries from patients with normal hearing undergoing surgical removal of rare meningiomas anterior to the brainstem via a transcochlear approach." (PMID 30971872, 2019). "By analyzing serum levels of brain-derived neurotrophic factor (BDNF) in 94 patients at diagnosis, we found higher BDNF levels in high-neural glioblastoma compared to low-neural glioblastoma, patients with meningioma (n = 13) and healthy individuals (n = 19)." (PMID 38760585, 2024).
metabolic dysfunction-associated steatohepatitis (2 papers, 2022 to 2024). Metabolic dysfunction-associated steatohepatitis (MASH, formerly known as nonalcoholic steatohepatitis or NASH) is a type of fatty liver disease. "We recently reported that reduced BDNF is associated with the development of one of the metabolic diseases, metabolic dysfunction-associated steatohepatitis (MASH), in two independent genetically engineered mouse lines with reduced BDNF expression." (PMID 38672461, 2024).
metastatic cancer (2 papers, 2020 to 2021). A carcinoma which has spread from the original site of growth to another anatomic site. "This phenomenon may explain the different TrkB receptor and BDNF expression observed between primary and metastatic cancer cells derived from the same patients." (PMID 33294440, 2020).
morphine dependence (2 papers, 2020 to 2022). Strong dependence, both physiological and emotional, upon morphine. "From this, it can be concluded that the treatment effect of sinomenine on morphine dependence may be related to the BDNF/Ntrk2 signaling pathway." (PMID 32670209, 2020). "A dose of 10 mg/kg of AG inhibited the development of morphine dependence in male Wistar rats and counteracted the effects of morphine to decrease the proliferation of hippocampal neural progenitors in the granule cell layer and the levels of hippocampal cAMP, pCREB, and BDNF." (PMID 34997272, 2022).
multiple system atrophy (2 papers, 2017 to 2021). Multiple system atrophy (MSA) is a neurodegenerative disorder characterized by autonomic failure (cardiovascular and/or urinary), parkinsonism, cerebellar impairment and corticospinal signs with a median survival of 6-9 years. "Oligodendroglial cells OLN-93 stably expressing either a human wild type or a mutant A53E α-synuclein (multiple system atrophy associated mutant) reduced BDNF mRNA to practically unmeasurable levels." (PMID 28751856, 2017). "Decreased levels of neurotrophic factors such as glial derived neurotrophic factor (GDNF), brain derived neurotrophic factor (BDNF), and insulin-like growth factor 1 (IGF1) have been identified in human brains with multiple system atrophy and in mouse models." (PMID 34512258, 2021).
Myalgia (2 papers, 2020 to 2023). "The first one reported a decrease in NGF and BDNF in the saliva and only an increase in plasma BDNF in patients with TMD-myalgia." (PMID 37569811, 2023). "The main findings were significantly different levels of salivary glutamate, NGF, and BDNF in patients with a diagnosis of TMD-myalgia compared to pain-free healthy controls." (PMID 32842964, 2020). "The main aim of this study was therefore to compare the concentration of glutamate, 5-HT, NGF, BDNF, and SP in saliva and plasma from a well-defined group of TMD-myalgia patients with a matched healthy pain free control group." (PMID 32842964, 2020). "Patients with TMD-myalgia further had lower levels of salivary NGF and BDNF, but higher plasma BDNF." (PMID 32842964, 2020). "The concentrations of NGF and BDNF, together with glutamate, serotonin, and SP, in saliva and plasma from a well-defined group of patients with chronic TMD-myalgia (n = 39) and in a group of pain-free controls (n = 39) in a clinical examination have been evaluated." (PMID 37569811, 2023). "Plasma BDNF levels on the other hand, showed as expected higher levels in TMD-myalgia." (PMID 32842964, 2020). "The present study showed that patients with a diagnosis of TMD-myalgia had significantly higher levels of salivary and plasma glutamate as well as plasma BDNF compared to healthy pain-free individuals, suggesting that these may be indicative biomarkers for TMD-myalgia." (PMID 32842964, 2020).
neurodegenerative diseases of the eye (2 papers, 2022). "This study is an important first step toward the development of a pigment epithelial cell-based BDNF gene therapy that could be used as an advanced therapy medicinal product (ATMP) for the treatment of neurodegenerative eye diseases." (PMID 36361771, 2022).
Neurodevelopmental delay (2 papers, 2020 to 2025). "Pathophysiological events related to prematurity and birth by Caesarean section appear to depress BDNF in cord blood and early breast milk, may interfere with the feedforward regulation of BDNF-5-HT axis and may result in neurodevelopmental delay." (PMID 32552911, 2020). "Studies have shown that PAH exposure during pregnancy is inversely related to cord blood plasma BDNF levels, and it has been found that the relationship between PAH exposure during pregnancy and offspring neurodevelopmental delay can be explained by lower cord blood plasma BDNF levels." (PMID 41012347, 2025).
Neurogenic bladder (2 papers, 2010 to 2024). A type of bladder dysfunction caused by neurologic damage. "Previous studies have reported the neuroprotective therapeutic effects of BDNF-eMSC in neonatal hypoxic-ischemic, traumatic brain injury, and neurogenic bladder models in rats." (PMID 38886817, 2024). "In our study, endogenous BDNF and NT-3 levels in the spinal cord and bladder were unchanged after hMSCs transplantation and these results may explain unrecovered neurogenic bladder." (PMID 20846445, 2010).
neuroma (2 papers, 2017 to 2024). A tumor that grows from a nerve or is composed of nerve cells and nerve fibers. "Deficiencies in the BDNF-trkB signaling pathway render neuroma formation difficult, and even the peripheral nerve is completely transected, suggesting that this signal could be a potential target for neuroma prevention and/or therapeutic intervention." (PMID 28072837, 2017). "Studies have pinpointed crucial factors, including nerve growth factor (NGF), brain-derived neurotrophic factor (BDNF), and various cytokines, as key players in the formation and maintenance of neuromas." (PMID 38672500, 2024).
Non-alcoholic fatty liver disease (2 papers, 2023 to 2025). "Physical activity not only upregulates BDNF/TrkB/CREB signaling pathway but also increases insulin sensitivity BDNF is a known myokine associated with physical activity in patients with non-alcoholic fatty liver disease." (PMID 36787304, 2023).
obesity syndrome (2 papers, 2013 to 2021). "Thus, obesity syndrome induced by BDNF insufficiency could result from either diminished anorexigenic activity of BDNF or structural defects in neural circuits that are important for the control of energy homeostasis." (PMID 23519010, 2013).
Onset (2 papers, 2020 to 2025). The age group in which disease manifestations appear. "Apolipoprotein E4 (ApoE4) has been identified as a significant genetic risk factor for late-onset Alzheimer’s disease, as it has been associated with reduced BDNF levels and inhibited BDNF mRNA expression." (PMID 40430064, 2025).
oral cancer (2 papers, 2023 to 2025). "In addition, the tumor-released BDNF contribution to oral cancer pain via peripheral TrkB activation was studied in a mouse orthotopic xenograft model (tongue tumor)." (PMID 37569811, 2023). "Additionally, another study indicated that changes in the expression of neurotransmitter-related genes, such as BDNF and COMT, in oral cancer patients may be associated with sleep disorders and anxiety." (PMID 40282437, 2025). "In addition, oral cancer cells can also release brain-derived neurotrophic factor (BDNF), which activates TrkB receptors in peripheral nerves, leading to nerve hypersensitivity and exacerbating pain in patients with oral cancer." (PMID 40282437, 2025).
pancreas diseases (2 papers, 2017 to 2021). "Concerning AUD-related variables, AUD patients with liver and pancreas diseases showed even lower concentrations of BDNF (p<0.05)." (PMID 29108028, 2017). "In fact, abstinent AUD patients with liver and/or pancreas diseases had lower BDNF concentrations relative to AUD patients with no disease [74.41 (95% CI = 43.77–126.51) pg/mL and 152.18 (95% CI = 118.15–196.03), respectively]." (PMID 29108028, 2017).
pancreatitis (2 papers, 2010 to 2025). Inflammation of the pancreas. "Based on the link between NT3 and the BDNF pathway, we sought to test whether serum BDNF levels were altered in pancreatitis pain patients." (PMID 39674387, 2025). "Interestingly, in pancreatitis BDNF content was reported to be correlated with pain intensity and exogenous application of BDNF has been shown to excite and sensitize some cutaneous nociceptive terminals (apparently via TrkB)." (PMID 21138586, 2010).
postherpetic neuralgia (2 papers, 2021 to 2024). "Pregabalin was reported to increase serum BDNF levels in a recent randomized, double-blind, controlled study on patients with thoracic postherpetic neuralgia." (PMID 33628271, 2021).
pulmonary TB (2 papers, 2020 to 2022). "Thus, the present study aimed to evaluate the efficacy of the administration of CUR on lung disease evolution, neuroinflammation, the Nrf2 and BDNF expression and behavioral alterations in a murine model of pulmonary TB." (PMID 35216083, 2022). "We also evaluated the BDNF levels in the murine model of pulmonary TB." (PMID 33322180, 2020).
renal cell carcinoma (2 papers, 2009 to 2016). "Therefore, considering all the previous evidences, we have focused the study on the relationship between pro-BDNF/p75NTR and its possible pro-survival role in renal cell carcinoma." (PMID 27120782, 2016). "This study highlights the function of p75NTR and pro-BDNF in renal cell carcinoma." (PMID 27120782, 2016). "Considering our previous results and to study the functions of pro-BDNF, p75NTR and TrkB, in clear cell RCC, two human cell lines derived from RCC were used, a primary renal cell carcinoma (786-O) and a metastatic renal cell carcinoma (ACHN)." (PMID 27120782, 2016). "Although the overexpression of TrkB, p75NTR and BDNF have been previously reported in several cancers as poor prognostic factors and to participate to tumor aggressiveness, their implication in renal cell carcinoma has not been previously reported." (PMID 27120782, 2016).
respiratory impairment (2 papers, 2023 to 2024). "It should be noted that in this study, post-hoc tests showed that patients with demonstrated bowel effects from BDNF treatment, or patients that had respiratory impairment at study onset, saw a benefit." (PMID 37692101, 2023).
Respiratory tract infection (2 papers, 2020 to 2023). An infection of the upper or lower respiratory tract. "Another source of high amounts of BDNF are platelets, which were shown to contain reduced amounts of BDNF during respiratory tract infections." (PMID 37047077, 2023).
retinal detachment (2 papers, 2022 to 2024). An eye emergency condition which may lead to blindness if left untreated. "This is in line with previous findings in cats, in which BDNF attenuated GFAP expression following retinal detachment." (PMID 35955747, 2022).
Salmonella Infections (2 papers, 2022). Infections with bacteria of the genus SALMONELLA. "A significant decrease in the expression of BDNF gene was observed in mice suffering from Salmonella infection." (PMID 35236424, 2022). "This might be due to that in this study Salmonella infection was acute, which might be supported by that some stimuli such as stress and hypoxia activate the expression of BDNF." (PMID 35967771, 2022).
selenium deficiency (2 papers, 2018 to 2022). A nutritional deficiency disease resulting from inadequate selenium levels in the body, which can lead to impaired function of selenoproteins essential for antioxidant defense and thyroid hormone metabolism. "A rodent study found an association between selenium deficiency and decreased BDNF concentrations." (PMID 29747386, 2018).
sexual dysfunction (2 papers, 2024). Disturbances in sexual desire and the psychophysiologic changes that characterize the sexual response cycle and cause marked distress and interpersonal difficulty. "Alterations in the molecular profile of IL-8, BDNF, and IL-10 provide insights into the mechanisms underlying sexual dysfunction in these patients." (PMID 39796020, 2024).
spondyloarthritis (2 papers, 2018 to 2025). "For instance, a study involving 31 men and 18 women reported lower plasma BDNF concentrations in patients with spondyloarthropathy (n = 15), RA (n = 15) and OA (n = 10), compared to healthy subjects (n = 9)." (PMID 40222813, 2025).
systemic sclerosis (2 papers, 2010 to 2013). A chronic disorder, possibly autoimmune, marked by excessive production of collagen which results in hardening and thickening of body tissues. "In contrast, BDNF production is unchanged in B and T cells in systemic sclerosis patients compared to healthy controls." (PMID 24223945, 2013). "In contrast, serum BDNF levels are decreased in systemic sclerosis, reflecting the vascular aspect of the disease." (PMID 24223945, 2013).
Thiamine deficiency (2 papers, 2020 to 2022). Thiamine deficiency is a condition that occurs due to not enough thiamine (vitamin B1). "Importantly, BDNF expression was reduced by ethanol exposure, whereas administration of exogenous BDNF was sufficient to restore LTP deficits in the hippocampus of rats in response to pyrithiamine-induced thiamine deficiency." (PMID 35706690, 2022).
ulcer (2 papers, 2020 to 2025). "Furthermore, we did not assess the presence and expression of the corresponding receptor, TrkC, or the receptors for other neurotrophic factors (TrkA for NGF, TrkB for BDNF) in the ulcer tissue." (PMID 39550735, 2025). "In the clinical treatment of diabetic foot, HUC-MSCs could be targeted to the ulcer and increase the formation of vascular endothelial growth factor (VEGF) and brain-derived neurotrophic factor (BDNF)." (PMID 33261658, 2020).
acanthamoebiasis (1 paper, 2022). "The likely role of BDNF and NT-3 in neuroprotection in cerebral acanthamoebiasis is also supported by the fact that immunocompetent mice with acanthamoebiasis at 8 dpi showed typical neurological symptoms such as circular marching and aggression." (PMID 35563321, 2022). "In this study, we observed significant upregulation of BDNF in the cerebral cortex at the beginning of acanthamoebiasis in immunocompetent mice (A)." (PMID 35563321, 2022). "This study demonstrated that BDNF and NT-3 play significant roles in the early stages of acanthamoebiasis in immunocompetent hosts." (PMID 35563321, 2022). "Thus, to clarify the role of NT in the cerebral cortex and hippocampus during acanthamoebiasis in relation to the host immune status, the purpose of this study was to determine how brain acanthamoebiasis affects the concentrations of the neurotrophins BDNF, NGF, NT-3, and NT-4." (PMID 35563321, 2022). "With the progression of neurodegenerative diseases, the phenotype of lymphocytes changes, and they stop secreting BDNF; it is possible that this process occurs also in the late stages of acanthamoebiasis, which might explain the significant contribution of BDNF at the beginning of acanthamoebiasis." (PMID 35563321, 2022). "However, the clinical and biological mechanisms behind the lower BDNF levels in the late stages of acanthamoebiasis are not fully known." (PMID 35563321, 2022).
acromegaly (1 paper, 2026). Acromegaly is an acquired disorder related to excessive production of growth hormone (GH) and characterized by progressive somatic disfigurement (mainly involving the face and extremities) and systemic manifestations. "This study compared the cognitive performance and serum BDNF and proBDNF levels between treatment‐naïve patients with acromegaly and healthy controls." (PMID 41550023, 2026). "In line with this hypothesis, patients with acromegaly had significantly decreased serum BDNF levels and increased proBDNF levels, which may indicate disrupted neurotrophic signaling and enhanced neurodegenerative processes." (PMID 41550023, 2026). "Compared to controls, the acromegaly group had significantly lower MoCA and MMSE scores (p < 0.001), reduced serum BDNF levels (p < 0.001), and elevated proBDNF levels (p = 0.007)." (PMID 41550023, 2026).
Acute hepatitis (1 paper, 2026). Acute hepatic injury resulting from inflammation typically accompanied by increased serum alanine transaminase activity. "BDNF and its mimetic peptide BDP12 represent promising therapeutic candidates for treating acute hepatitis-mediated ALI/ALF." (PMID 41881032, 2026). "In conclusion, this study identifies hepatocyte-derived BDNF as an endogenous antagonist of TLR4 and a critical immune checkpoint in acute hepatitis." (PMID 41881032, 2026).
ameloblastoma (1 paper, 2020). The most common odontogenic tumor, arising from the epithelial component of the embryonic tooth and usually affecting the molar-ramus region of the mandible or maxilla. "Using immunofluorescent staining, we detected expression of the neurotrophins NGF (Nerve Growth Factor) and BDNF (Brain Derived Neurotrophic Factor), as well as their receptors P75/NGFR, TRKA and TRKB, in human ameloblastoma biopsies." (PMID 32155948, 2020). "Taken together, our results show that ameloblastomas exhibit stem cell potential, express NGF, BDNF, and neurotrophin receptors, and create contacts with trigeminal neurons that might play key roles in the onset and progression of these tumors." (PMID 32155948, 2020). "Additionally, we showed that ameloblastomas express the neurotrophic factors NGF and BDNF, as well as their receptors TRKA, TRKB, and P75/NGFR, which are responsible for their innervation by trigeminal axons in vivo." (PMID 32155948, 2020).
aneurysm (1 paper, 2023). Bulging or ballooning in an area of an artery secondary to arterial wall weakening. "Serum BDNF, TNF-α, caspase-3, AChE, and BChE levels were measured in 20 patients with spontaneous SAH due to aneurysms." (PMID 37873057, 2023).
anti-phospholipid syndrome (1 paper, 2013). "NT-3 is upregulated only in severe flares of the disease, and BDNF levels are closely related to anti-phospholipid syndrome." (PMID 24223945, 2013). "Although numbers of NGF-producing cells were independent of clinical SLE profiles, CD19+ BDNF-producing B cells were dramatically decreased in patients with an associated anti-phospholipid syndrome (40.2 ± 8.9 vs 80.5 ± 22.05, p=0.03)." (PMID 24223945, 2013).
artery stenosis (1 paper, 2022). "It was suggested that SAH, IL-1β, Hcy, TNF-α, BDNF were positively correlated with the number of coronary artery stenosis vessels(r = 0.421, 0.533, 0.301, 0.265, 0.678, P = 0.016、0.009、0.023、0.036、0.004)." (PMID 35282820, 2022).
auditory neuropathy (1 paper, 2022). A hearing disorder characterized by impaired transmission of signals through the auditory nerve, resulting in mild to severe hearing loss and poor speech perception. "Neurotrophic factors such as BDNF, CNTF, NT3, and NGF have been tested in animal models of auditory neuropathy in different studies." (PMID 35720065, 2022).
autonomic disorders (1 paper, 2020). "It is unclear how hippocampal low levels of BDNF (reflected by low circulating BDNF) is related to autonomic disorders in Dlow and Dhigh." (PMID 33344701, 2020).
behavior (1 paper, 2020). The internally coordinated responses (actions or inactions) of animals (individuals or groups) to internal or external stimuli, via a mechanism that involves nervous system activity. "KXS is effective in improving behavior disorders by activating TrkB/ERK/CREB/BDNF and TrkB/PI3 K/CREB/BDNF pathways and influencing various inflammatory pathways, such as IL-6 and TNF-α." (PMID 32973539, 2020).